ADAMTS7P1 (ADAMTS7 pseudogene 1)
Synonyms: ADAMTS7P2
Gene: Transcribed unprocessed pseudogene on chromosome 15 (82,298,553 to 82,334,609, forward strand). Ensembl gene ENSG00000274376.
Diseases named in the same sentence as ADAMTS7P1 in open-access papers:
ADAMTS7P1 is named in the same sentence as 1 disease in open-access papers, as found by Europe PMC text mining. Sharing a sentence is not in itself a finding about the gene and the disease. The quoted sentences say what the papers report.
Hypertension (1 paper, 2018). The presence of chronic increased pressure in the systemic arterial system. "The ADAMTS7P1 gene at 15q25.2 has not been reported to be associated with blood pressures or hypertension." (PMID 30693016, 2018).